PDCD1 (programmed cell death 1)
Diseases named in the same sentence as PDCD1 in open-access papers (continued):
Sharing a sentence is not in itself a finding about the gene and the disease.
tumor (continued). "During immune escape, the presence of immune checkpoint molecules, such as programmed cell death 1 (PD-1) and its ligand programmed death-ligand 1 (PD-L1), would hamper the tumor killing activity of CD8+ T cells." (PMID 38031188, 2023). "As is well known, tumor immune escape is linked to crucial immunological checkpoint proteins, including CTLA-4 and PDCD-1." (PMID 36899339, 2023). "Including only PDCD1-CD274 as an inhibitor (purple lines) resulted in a poor fit to the number of CTLs counted inside the tumor, as well as the dynamics of PDCD1 and CD274 themselves." (PMID 37182110, 2023). "By analyzing datasets derived from The Cancer Genome Atlas (TCGA) database, we observed a significant positive correlation between LGALS1 and PDCD1 in five tumor types, with the exception of UCEC." (PMID 37833788, 2023). "Immune checkpoint blockade aims at boosting tumor-specific T cells by breaking immunoevasion mediated by inhibitory checkpoint molecules, such as programmed cell death-1 (PD-1)/PD-ligand 1 (PD-L1)." (PMID 36768665, 2023). "Recent studies have shown promising synergistic effects of the combination of programmed cell death-1 (PD-1)/programmed cell death-ligand 1 (PD-L1) inhibitors and radiotherapy in improving tumour regression." (PMID 37802608, 2023). "In tumor cell-enriched regions, PDCD1 expression was negatively correlated with the levels of monocytes and CD4+ memory-activated T cells." (PMID 37151882, 2023). "in the ShortHER phase III trial found that HER2-enriched BC tumor with mutated PIK3CA had an upregulated expression of MKI67, MYBL2, ESR1, PDCD1 and other genes, but only MYBL2 and PDCD1 were related with a better DFS." (PMID 37313470, 2023). "PD-1/PD-L1 (programmed cell death-1/programmed cell death-ligand 1) inhibitors, known as a kind of immune checkpoint inhibitors (ICIs), have revolutionized the paradigm of tumor therapy." (PMID 36969245, 2023). "Zimberelimab was added due to the weak effect of initial therapy after 2 crucial programmed cell death-1 (PD-1) therapy biomarkers, high microsatellite instability (MSI-H) and high tumor mutational burden (TMB-H) genome features, were confirmed." (PMID 36820603, 2023). "Through an optimized protocol, researchers successfully inserted an anti-CD19 CAR cassette into the PDCD1 locus, which exhibited a superior ability to eradicate tumor cells in xenograft models." (PMID 38516299, 2023). "In the field of tumor immunotherapy research, the six immune checkpoints PDCD1, CD274, CTLA-4, LAG-3, TIGIT, and HAVCR2 can inhibit the proliferation, activation and effector functions of T cells, and maintain the immune homeostasis in the body." (PMID 37810780, 2023). "PD-L1 on tumor cells binds to programmed cell death 1 (PD-1, PDCD1) on T cells, which is colocalized with the TCR, inhibiting T-cell activation and inducing T-cell exhaustion." (PMID 36765793, 2023). "The surface receptor, programmed cell death-1 (PD-1), plays a role in suppressing T cell anti-tumor activities and allowing tumor cells to evade the immune response." (PMID 36672682, 2023). "Programmed cell death 1 (PD-1) and programmed cell death ligand 1 (PD-L1) are well-known immune check points, and its ligand negatively regulates the cytotoxicity of anti-tumor effector cells." (PMID 36673082, 2023). "Programmed Cell Death-1/ Programmed Death-ligand 1 (PD-1 / PD-L1) inhibitor therapies targeting immunocytes induce persistent tumor remission in various cancers." (PMID 36698098, 2023). "The modest and tight expression of IL-12 from the PDCD1 locus was sufficient to enhance the anti-tumor activity of NY-ESO-1 TCR-T cells." (PMID 36793716, 2023). "We observed recovery of 97% of sgRNAs from tumor samples and strong enrichment of sgRNAs targeting the Pdcd1 gene (FDR-adjusted P < 1 × 10–16)." (PMID 38099496, 2023).
tumor (continued). "Current agents are monoclonal antibodies targeting either cytotoxic T-lymphocyte antigen 4 (CTLA-4) programmed cell death 1 (PD-1) or its ligand PD-L1 to potentiate anti-tumor immune responses." (PMID 37445704, 2023). "In cancer, tumor cells often express programmed death-ligand 1 (PD-L1) to bind to their receptor the programmed cell death-1 (PD-1) in the tumor-infiltrating lymphocytes (TILs) to suppress their antitumor actions." (PMID 38082443, 2023). "Our finding suggests that different immunosuppressive mechanisms (i.e. PDCD1 immune checkpoint activation and tumor F. nucleatum enrichment) tend to be used by different tumor subgroups." (PMID 37538192, 2023). "We found that the proportion of CD8+ T cells expressing proinflammatory/pro‐tumour cytokines/molecules was higher than that of other immune cells, especially Ltb, Pdcd1, Cxcr6 and Il1b." (PMID 37997519, 2023). "A notable association was observed across risk score and the expression of CTLA4, HAVCR2, PDCD1, PDCD1LG2, and TIGIT, indicating risk scores represent tumor-induced immunosuppression." (PMID 37404760, 2023). "While FOS (c-Fos) and JUN (c-Jun) are known to induce T cell activation, FOS previously has been shown to suppress T cells through PDCD1 and promote tumor progression." (PMID 36305874, 2023). "Programmed cell death-1 acts as a co-inhibitory receptor because it binds to T cells by binding to the PD-L1 ligand expressed in tumor cells, thereby preventing T cell activation and immunological exhaustion." (PMID 37047618, 2023). "IHC staining of CD3 and PDCD1 confirmed our findings that exhaustion genes were more frequently expressed within tumor regions." (PMID 38123589, 2023). "The interaction between PD-L1 and PDCD1/PD-1 is a way to reduce anti-tumor immunity and evade immune system damage, thereby promoting tumor survival." (PMID 37976136, 2023). "Immune checkpoint inhibitors, such as programmed cell death-1(PD-1) mAb, have been used to relieve the restrictions of CTLs28, but the application of PD-1 mAb alone cannot maximize the tumour killing effects of CTLs29." (PMID 37076492, 2023). "The expanding role of immune-based therapies for KS and the reliance of this tumour on the programmed-cell death 1 pathway as a mechanism of immune escape further strengthens the rationale for a classification system centred on the host immune function." (PMID 37106396, 2023). "COL1A2 was positively correlated with CD274, CTLA-4, and PDCD1 based on TIMER data which was adjusted by tumor purity." (PMID 37805556, 2023). "Combination treatment with SNA and anti-programmed cell death-1 (PD-1) antibody slowed OS tumor growth and improved survival by inhibiting MDSCs." (PMID 37894474, 2023). "Tumor angiogenesis is also regulated by programmed cell death-1 (PD-1), which suppresses the antitumor function of CD8+ T cells." (PMID 37445657, 2023). "The combination of multiple CRISPR-Cas9 editing of TRAC, TCRβ constant, and PDCD1 with introduction of a cancer-specific TCR transgene (NY-ESO-1) improved anti-tumor immune responses and reduced TCR mismatches in a phase I human clinical trial." (PMID 37200626, 2023). "So far, the results from three phase 1 trials have been published, but the results are inconclusive for the enhanced anti-tumor effect produced by the disruption of PDCD1." (PMID 37190012, 2023). "The majority of tumors can utilize PDCD1 mediated immunosuppression pathway to escape the surveillance of the immune system to promote tumor survival." (PMID 36776322, 2023). "Collectively, our results suggest that the target-dependent and moderate expression of IL-12 derived from the PDCD1 locus provides an effective strategy to enhance the anti-tumor function of TCR-T cells." (PMID 36793716, 2023). "Immune checkpoint inhibitors (ICIs) target the cytotoxic T lymphocyte antigen 4 (CTLA-4)/CD28/programmed cell death 1 (PD-1)/programmed cell death 1 ligand 1 (PD-L1) axis, leading to immune activation in the tumor microenvironment." (PMID 37554766, 2023).
tumor (continued). "Programmed death-ligand 1 (PD-L1), expressed on the surface of tumor cells, can bind to programmed cell death-1 (PD-1) on T cells." (PMID 37228770, 2023). "The combination of CXCR4 therapeutic agent blockade and PDCD1 resulted in the reduction of suppressive leukocytes and promoted the transition of M2-to-M1 macrophage polarization within the tumor." (PMID 38044943, 2023). "A notable correlation was observed between risk score and expression of CTLA4, HAVCR2, PDCD1, PDCD1LG2, and TIGIT, indicating risk scores represent tumor-induced immunosuppression." (PMID 37404760, 2023). "Our findings suggest that different immunosuppressive mechanisms (i.e. PDCD1 immune checkpoint activation and tumor F. nucleatum enrichment) tend to be used by different tumor subgroups." (PMID 37538192, 2023). "RNAseq data from 60 tumor samples obtained prior to chemotherapy and also showed improved overall survival in patients with high PDCD1 and CD8A expression, median OS 20.5 vs 9.3 months (HR 0.475, p = 0.017)." (PMID 36781556, 2023). "We examined the expression levels of PD-1 (PDCD1), PD-L1, and CTLA4 (cytotoxic T-lymphocyte associated protein 4) in tumor and normal groups." (PMID 37251440, 2023). "With the advent of facile gene editing technologies, CRISPR-Cas9 has been used for disruption of the PDCD1 gene encoding for PD1, and this has resulted in the enhancement of anti-tumor effects of CAR-T in animal models." (PMID 37190012, 2023). "To explore the potential role of tumor cell-intrinsic PD-1 receptor in CRC tumor cells, we knocked down PDCD1 expression by using a short interfering RNA (siRNA) which target the sequence of PDCD1 in SW480 cells." (PMID 37476193, 2023). "Recently, the role of immunotherapy in tumor treatment has been widely investigated, especially for cytotoxic T-lymphocyte associated protein 4 (CTLA-4) and programmed cell death-1 (PD-1) inhibitors." (PMID 37842200, 2023). "Among diverse immunotherapy strategies, ICB therapy is an unprecedented anti-tumor therapy by blocking inherent immune inhibiting factors, such as programmed cell death 1 (PD-1) or their ligands PD-L1, and cytotoxic T-lymphocyte antigen 4 (CTLA-4)." (PMID 36810281, 2023). "IFN-γ–secreting CD4+ TILs also expressed the coinhibitory marker programmed cell death 1 (PD-1), consistent with published signatures of tumor-reactive CD4+ TILs." (PMID 36512410, 2023). "In this study, OCLN expression was found to be significantly negatively correlated with PDCD1 and CTLA4 expression, which implicated the role of OCLN in regulating tumor immunology in KIRC." (PMID 37809090, 2023). "It was discovered that IP-score was closely associated with PDCD1, CD274, CTLA-4, and LAG3 expression levels in urinary solid tumours, indicating that IP-score was closely associated with tumour escape and immune depletion." (PMID 36700205, 2022). "To further explore the role of G6PD in the tumour immune microenvironment, we also analysed the association between G6PD and immune checkpoint molecules (PDCD1, CD274 and CTLA4)." (PMID 35712981, 2022). "While radiation is cytotoxic, it also impacts the tumor itself, e.g., by upregulation of Programmed Cell Death-Ligand 1 (PD-L1) and Programmed Cell Death-1 (PD-1), and its microenvironment by increased anti-tumor response mechanisms." (PMID 35740613, 2022). "Remarkably, after narrowing the search scope to genes that were highly expressed in tumor tissues, LAG3, PDCD1, and RUFY4 were found to be associated with the high degree of immune infiltration of Tregs and TFHs." (PMID 35135552, 2022). "It has been shown that high levels of PD-1 (PDCD1) expression correlate with increased numbers of tumor-infiltrating Tregs and decreased numbers of effector T cells in the TME of CRC, which can be reversed by immune checkpoint blockades (ICB)." (PMID 36544770, 2022). "Monoclonal antibodies (abs) targeting the programmed cell death 1 (PD-1) immune checkpoint pathway have revolutionized tumor therapy." (PMID 35864188, 2022).
tumor (continued). "Programmed cell death 1 (PD-1) and its ligand (PD-L1) have become one of the most studied receptors that brings a recent breakthrough in new tumor immunotherapy for immune checkpoint." (PMID 35986302, 2022). "In vivo, STS suppressed tumor growth and enhanced the antitumor effect of the programmed cell death 1 (PD1) antibody." (PMID 35571116, 2022). "Our study on tumor-infiltrating NK cells have been conducted in mice with a general deletion in the PDCD1 gene." (PMID 36185379, 2022). "This limits their anti-tumor activity and induces the expression of immune regulatory molecules cytotoxic T-lymphocyte associated protein 4 (CTLA-4) and programmed cell death 1 (PD-1)." (PMID 35327609, 2022). "Immunotherapy utilizing programmed cell death-1 (PD-1)/PD-L1 inhibitors has been regarded as a rising hope for tumor patients, and their effects have been demonstrated in many clinical trials." (PMID 35860268, 2022). "We found that CSF-1R was significantly correlated with tumor-related immunosuppressive molecules including PDCD1, CTLA4, CD80, CD86, HAVCR2, etc.." (PMID 35444953, 2022). "We analyzed bulk RNA-seq from NSCLC tumor samples from three randomized clinical trials with atezolizumab and assessed how gene expression of CD226, PDCD1 (encoding PD-1), and TIGIT associated with clinical outcomes." (PMID 35263569, 2022). "Meanwhile, astragaloside IV combined with a PDCD1(PD-1) inhibitor exhibited a synergistic effect on inhibiting tumor growth and T cell infiltration." (PMID 35600371, 2022). "Immune checkpoint molecules, including programmed cell death-1 (PD-1) and programmed cell death ligand-1 (PD-L1), play important roles in oncogenesis by maintaining an immunosuppressive tumor microenvironment." (PMID 36338673, 2022). "Programmed cell death 1/programmed cell death ligand 1 (PD1/PDL1) axis plays an important role in tumor progression and immune surveillance evasion." (PMID 36467413, 2022). "According to tumor pathological studies, Pdcd1 expression is very high in T cells in the tumor microenvironment in cancer patients, and it is correlated with tumor cell malignancy." (PMID 35190965, 2022). "The inhibitory receptor programmed cell death-1 (PD-1, CD279) is a key therapeutic target to treat immune and inflammatory disorders as well as to stimulate the anti-tumour immune response." (PMID 35930205, 2022). "In conclusion, we developed an anti-PD-1-resistant B16F10 tumour model using human Pdcd1 transgenic mice." (PMID 36077671, 2022). "The membrane of T cells of this nanoparticle not only serves as a protective shell for drug delivery, but also selectively binds to the PD-L1 of tumor cells as a programmed cell death-1 (PD-1) C antibody." (PMID 36005653, 2022). "In previous pre-clinical murine cancer models, co-blockade of LAG3 and PDCD1 induced an up-regulation anti-tumor response." (PMID 34998385, 2022). "The efficacy of ICI therapy in suppressing programmed cell death-1 (PD-1) or programmed cell death ligand-1 (PD-L1) to enhance T cell functions is significantly correlated with host immune systems and the tumor microenvironment." (PMID 36313898, 2022). "Immune checkpoint inhibitors (ICIs) enable the reversion of T cell suppression and enhance anti-tumor immune responses by blocking programmed cell death 1 (PD-1, PDCD1)/programmed death-ligand 1 (PD-L1, CD274) signaling." (PMID 35992797, 2022). "A similar approach was applied to dissect tumor-specific B cell proliferation networks involving PD1 (PDCD1), PDL1 (CD274), and CTLA4." (PMID 35804895, 2022). "Next, considering the potential tumor suppressor role of EPHX3 in HNSCC, we examined the association between EPHX3 and CD274, IL1B, IL1A, PDCD1, and PDCD1LG2." (PMID 35401746, 2022). "According to recent clinical trials, a combination chemotherapy with DOX and nivolumab, a monoclonal antibody against Pdcd1, exhibited more effective anti-tumor activity in cancer patients." (PMID 35190965, 2022).
tumor (continued). "The expression of PDCD1 on cancer cells is considered to be a key mechanism leading to tumor immune evasion." (PMID 35444953, 2022). "The protein-protein interaction of Programmed Cell Death-1/Programmed Cell Death-Ligand 1 (PD1/PDL1) leads to tumor resistance to apoptosis and promotes tumor progression." (PMID 35769111, 2022). "The Programmed Death Ligand 1 (PD-L1) is one of two ligands of the Programmed Cell Death 1 (PD-1) protein, which is expressed in a variety of cells, including tumours, where it functions to modulate immune reactions." (PMID 35743743, 2022). "To explore mechanism of GIMAP4 underlying tumor-immune regulation, we calculated the correlations between GIMAP4 and 5 ICPs (CD274, CTLA4, TIGIT, LAG3, and PDCD1) and identified similar trends in their expression." (PMID 36246963, 2022). "Prospective cohort biomarker study of 52 patients with solid cancer tumours that completed programmed cell death-1 inhibitors (PD-1i) therapy." (PMID 36012771, 2022). "Programmed cell death 1 (PD1) blocking antibodies that enhance tumor immunity are currently under investigation in MSI high CRCs." (PMID 35912261, 2022). "Programmed cell death 1 (PD-1), an inhibitory receptor, has a key effect in the control of autoimmune diseases, tumours, and infective diseases." (PMID 36499036, 2022). "The data revealed that the exhaustion status of CD8+ T cells was significantly improved in MPR tumor lesions, with reduced expression of exhausted markers, such as PDCD1, CTLA4, LAG3, and TIGIT." (PMID 35831283, 2022). "Specifically, DCIS T Lymphocytes exhibited significant upregulation of the Pdcd1 gene, which was lower in the Tumor state." (PMID 35851387, 2022). "The CIBERSORT database and Spearman correlation analysis indicated that SLC1A5 was correlated with eight types of tumor-infiltrating immune cells and immune checkpoints, including PD-L1(CD-274) and PD-1(PDCD1)." (PMID 35305616, 2022). "High-dose vitamin C can decrease tumor volumes combined with anti-PDCD-1(PD-1) and anti-CTLA4 and enhance CD8+ T cell cytotoxic activity." (PMID 35600371, 2022). "Programmed cell death 1 (PD-1) pathway blockade enhances tumor antigen-specific CD8+ T cell responses." (PMID 34991708, 2022). "Research has shown that various cancers use the PD-L1 and programmed cell death-1 (PD-1) immune checkpoints to evade T cell immunity, and blocking their interaction has significant anti-tumor effects in patients with advanced cancer." (PMID 35585970, 2022). "PD-L1CPS was higher in tumor-infiltrating immune cells (r = 0.387, p = 0.001) and positively correlated with programmed cell death-1 and forkhead box P3 + regulatory T cell (FOXP3 + Treg) infiltration (r = 0.443, p < 0.001; r = 0.532, p < 0.001)." (PMID 36376881, 2022). "Programmed cell death 1 (PD-1) receptor is expressed on different immune cells, including tumor-infiltrating lymphocytes (TILs), and binds to PD-L1, which is expressed on myeloid regulatory cells and nonimmune cells such as malignant cells." (PMID 35499071, 2022). "SPI1 expression was positively and strongly associated with T cell exhaustion markers (LAG3 and PDCD1,), and Treg cell markers (FOXP3 and CCR8), suggesting that high SPI1 expression level inhibits anti-tumor immunity." (PMID 36477668, 2022). "The combination of G-1 pretreatment and the systemic delivery of an anti-programmed cell death 1 (PD-1) antibody inhibited tumor development and extended the life of melanoma cells." (PMID 35805104, 2022). "Our study found that tumor samples in the high-risk group expressed higher levels of BRCA1 and BRCA2 but lower levels of CTLA4 and PDCD1." (PMID 36704358, 2022). "On the other hand, tumor immunotherapy studies have been conducted in recent years targeting programmed cell death-1 (PD-1) and programmed death-ligand 1 (PD-L1)." (PMID 35145519, 2022).